COPS5 (COP9 signalosome subunit 5)
Diseases named in the same sentence as COPS5 in open-access papers (continued):
Sharing a sentence is not in itself a finding about the gene and the disease.
B cell lymphoma (1 paper, 2024). "Finally, Since COPS5 has been shown to be associated with the proliferation of DLBCL in several cell lines derived from subtypes of DLBCL, to further determine the role of COPS5 in B cell lymphoma, we depleted COPS5 in the B cell lymphoma cell lines Raji and SLVL using the CRISPR/Cas9 system." (PMID 38974382, 2024).
clear cell renal cell carcinoma (1 paper, 2024). "Alternatively, COPS3 may promote clear cell renal cell carcinoma progression by regulating phospho-AKT (Thr308), Cyclin D1, and Caspase-3 expression, while COPS5, -6, and -8 overexpression enhanced cellular proliferation, EMT, and vascular invasion." (PMID 38466642, 2024).
ischemic stroke (1 paper, 2023). A stroke disorder caused by obstruction of blood flow to the brain, due to thrombotic (local blood clot formation) or embolic (due to a blood clot or other material traveling from another site) event. "The data revealed that the expression of CSN5 (and its gene COPS5) in brain is prominent in neurons as well as microglia and is upregulated in experimental ischemic stroke, but seemingly not further upregulated upon inflammatory stimulation." (PMID 37597109, 2023).
male infertility (1 paper, 2025). The inability of the male to effect fertilization of an ovum after a specified period of unprotected intercourse. "Sertoli-specific Cops5 ablation resulted in age-dependent male infertility, despite normal initial development." (PMID 41509289, 2025). "We demonstrate that COPS5 is intrinsically required for Sertoli cell function and that its ablation will disrupt the BTB integrity, Sertoli cell polarity and spermatogenesis, leading to male infertility." (PMID 41509289, 2025).
muscle atrophy (1 paper, 2022). The loss of muscle tissue due to inactivity or disease. "In conclusion, we identified that CUL3 and COPS5 may be novel prognostic biomarkers in muscle atrophy based on bioinformatics analysis." (PMID 35815279, 2022). "Furthermore, CUL3 and COPS5 are related to the ubiquitin-proteasome pathway, which may provide useful ideas for the study of the pathogenesis of muscle atrophy." (PMID 35815279, 2022).
serous ovarian cancer (1 paper, 2020). "COPS5 has been reported to control proliferation and inhibits the expression of p27 in serous ovarian cancer." (PMID 32143396, 2020).
cancer (101 papers, 2008 to 2025). A tumor composed of atypical neoplastic, often pleomorphic cells that invade other tissues. "We previously confirmed that overexpression of Jab1/COPS5 in NPC is associated with increased resistance to cancer therapies and poorer survival." (PMID 36618352, 2022). "As an oncogene, Jab1/COPS5 is aberrantly overexpressed in several human cancers and implicated in facilitating carcinogenesis." (PMID 33292641, 2020). "Overexpression of COPS5 has been implicated in the pathogenesis of several types of cancer in humans and in some cases has correlated with poor prognosis." (PMID 21755009, 2011). "Jab1/COPS5 expression is associated with tumor progression and outcomes in many cancer patients." (PMID 29535627, 2018). "In TCGA pan‐cancer analysis, we found that COPS5 expression levels were higher in tumor tissues than in normal tissues in most cancer types." (PMID 40198582, 2025). "For example, the N-terminus is sufficient to interact with KPNA2 for TXNIP’s localization to the nucleus, while the C-terminus of TXNIP is critical for interactions with COPS5, to inhibit cancer cell proliferation." (PMID 38727583, 2024). "However, the full roster of cancer-relevant cargo mediated by COPS5, and the dysregulated pathway caused by inappropriate nuclear-cytoplasmic partition due to upregulation of COPS5, remain unclear and we will continue to unravel the underlying mechanisms in the future." (PMID 36135183, 2022). "Further, the Jab1/COPS5 inhibitor curcumin blocked TNFα-induced PD-L1 stabilization in various cancer cells." (PMID 29535627, 2018). "The mechanism of Jab1/COPS5 dysregulation in cancer patients still needs further exploration, but at least we can conceive that Jab1/COPS5 is a promising biomarker for cancer." (PMID 29535627, 2018). "Herein, we review advances in understanding the oncogenic role of Jab1/COPS5 in tumorigenesis as well as its therapeutic implications in combating cancer." (PMID 29535627, 2018). "Collectively, these results strongly support the association between COPS5 and SNAIL expression in the clinical cancer samples likely through the deubiquitinating activity of COPS5." (PMID 29755680, 2018). "The degree, duration, and tissue specificity required for Jab1/COPS5 blockade to inhibit cancer growth need to be deeply explored." (PMID 29535627, 2018). "Jab1/COPS5 has spurred a strong research interest in developing inhibitors of oncogenes/oncoproteins for cancer therapy." (PMID 29535627, 2018). "The Jab1/COPS5 locus which locates on chromosome 8q13.1, is found to be frequently amplified in human cancers." (PMID 29535627, 2018). "While Jab1/COPS5 is systemically expressed in both tumor tissues and normal tissues, Jab1/COPS5 expression levels in cancers are significantly higher than those in normal tissues." (PMID 29535627, 2018). "A growing body of evidence has interpreted that overexpression of Jab1/COPS5 is negatively correlated with p27 level and associated with worse prognosis in a variety of human cancers." (PMID 29535627, 2018). "In this paper, we present evidences demonstrating the importance of Jab1/COPS5 overexpression in several cancer types and recent advances in dissecting the Jab1/COPS5 upstream and downstream signaling pathways." (PMID 29535627, 2018). "Since Jab1/COPS5 overexpression is usually correlated with poor prognosis, development of Jab1/COPS5-specific inhibitors is likely to have a significant effect on cancer therapy." (PMID 29535627, 2018). "Collectively, our present study sheds light on the COPS5 deubiquitinating enzyme to control SNAIL-dependent metastasis and progression of COPS5-overexpressing cancers, and further implicates the new therapeutic strategy of cancer by targeting COPS5." (PMID 29755680, 2018). "Aberrant overexpression of Jab1/COPS5 is demonstrated to play a role in the pathogenesis of several types of human cancers and correlate with poor cancer prognosis." (PMID 29383106, 2017).
cancer (continued). "Jab1/COPS5 level has been shown to be associated with tumor progression and poor outcomes in many types of cancer patients." (PMID 29228627, 2017). "Our previous studies demonstrated that Stat3 and non-coding RNAs contribute to overexpression of Jab1/COPS5 in cancer, and highly expressed Jab1/COPS5 regulates DNA damage response, which confers chemotherapy and radiotherapy resistance to tumor cells." (PMID 29228627, 2017). "Increasing evidence indicates that dysregulation of Jab1/COPS5 activity contributes to tumorigenesis, which is functionally associated with cancer-related genes including p27, p57, SMAD4, NcoR, Trx and so on." (PMID 29228627, 2017). "We also investigated the relationship between COPS5 and survival of cancer patients in OncoLnc database." (PMID 29228627, 2017). "Although the effect of COPS5 upregulation on the resistance to ferroptosis inducers in multiple types of cancer remains to be validated, our collective findings convincingly support the critical role of elevated COPS5 expression in rendering HCC insensitive to ferroptosis." (PMID 40198582, 2025). "The downregulation of HIF1A and COPS5 has been shown to inhibit the proliferation and malignant behaviors of cancer cells, suggesting that inhibitors targeting the two proteins may have potential as anticancer therapeutics." (PMID 38360878, 2024). "Moreover, COPS5 is co-expressed with STAT3 in cancers, and MYC mediates this co-regulation associated with poor prognosis." (PMID 38974382, 2024). "In addition, inhibition of COPS5 by curcumin reduced the expression of PD-L1 and sensitized cancer cells to anti-CTLA4 treatment." (PMID 38466642, 2024). "Besides, COPS5 can regulate the deubiquitination of cullin, thereby controlling a variety of biological processes, which has been reported in a variety of cancers (liver, pancreatic, breast, etc)." (PMID 35463358, 2022). "It has been reported that COPS5 usually interacts with proteins or binds to miRNAs to regulate tumor progression, and it has also been shown to affect the metastatic potential of cancer cells by inhibiting SNAIL ubiquitination." (PMID 35815279, 2022). "To investigate the significance of SNAIL deubiquitination by COPS5 in cancer metastasis, we introduced the mutant forms of SNAIL protein (K98R/K137R/K146R, referred to as SNAIL-3KR) in A549 cells, which lacks three ubiquitination sites and therefore increased protein stability (data not shown)." (PMID 29755680, 2018). "Although Jab1/COPS5 locates in both nuclear and cytoplasmic, whether Jab1/COPS5 acts independently or as part of the CSN complex in cancers needs further investigation." (PMID 29535627, 2018). "Likewise, a recent study suggested that another pro-inflammatory cytokine, TNFα, which is secreted by macrophages, induces stabilization of PD-L1 on cancer cells through COP9 signalosome subunit 5 (CSN5)-mediated de-ubiquitination." (PMID 30062558, 2018). "In addition to its direct contribution in cancer cell invasion, COPS5 is known to regulate TGF-β signaling by binding to Smad7, which is the important signaling pathway for both metastasis and EMT." (PMID 29755680, 2018). "Collectively, COPS5 could be a good molecular target for cancer metastasis through SNAIL degradation." (PMID 29755680, 2018). "However, it lacks studies of Jab1/COPS5 in cancer patients with regard to chemotherapy response and cancer relapse." (PMID 29228627, 2017).
cancer (continued). "With detecting the Jab1/COPS5 expression, we could classify cancer patients into good and poor prognosis groups, select patients who have a high risk of postoperative relapse, and need strict follow-up and intense treatment." (PMID 29228627, 2017). "Those cancer patients with high expression of Jab1/COPS5 might particularly benefit from additional target therapy." (PMID 29228627, 2017). "However, when COPS5 is amplified and overexpressed in endocrine-resistant cancer cells, elevated COPS5/COP9 activity induces global NCoR protein degradation." (PMID 27375289, 2016). "Thanks to their smaller size and network structure, they provided compelling hypotheses on genes like COPS5 and CUL3, which lack genome-wide association with the disease but are related to cancer at the expression level and consistently interact with high scoring genes." (PMID 33735170, 2021). "Three regulatory mechanisms may contribute to the dysregulated expression of Jab1/COPS5 in cancer." (PMID 29535627, 2018). "However, the mechanism by which Jab1/COPS5 facilitates cancer progression remains largely elusive." (PMID 29535627, 2018). "However, Cops5 may alternatively or in addition represent another potential cancer-related interaction, as it is also known to play a critical role in cell proliferation, apoptosis, and regulation of genomic stability and DNA repair." (PMID 28587635, 2017). "Notably, COPS5 is mainly expressed in cellular nucleus of cancer cells." (PMID 27375289, 2016). "Indeed, COPS5 has been proposed as a target for anti-cancer drug development." (PMID 21283576, 2011). "The functional importance of COPS5 was also confirmed in DLBCL patients and knockout experiments, revealing the significant contribution to poor prognosis and cancer cell proliferation." (PMID 38974382, 2024). "Here, the authors examine cancer resistance mechanisms across seven bat species using in vitro and in vivo models, and identify HIF1A, COPS5, and RPS3 as related genes." (PMID 38360878, 2024). "Subsequently, TNF-α also inhibits the ubiquitination and degradation of PD-L1 protein through COP9 signalosome subunit 5 (CSN5), thereby enhancing the stability of PD-L1 and sensitizing cancer cells to immunotherapy." (PMID 38762484, 2024). "The transcriptomic and functional analyses reveal that the downregulation of three genes (HIF1A, COPS5, and RPS3) largely contributes to cancer resistance in MPI." (PMID 38360878, 2024). "COPS5 and COPS6 can prevent PD-L1 from degrading, thereby maintaining PD-L1 stability in cancer cells." (PMID 38466642, 2024). "Jab1/COPS5 expression is closely related to tumor progression and prognosis in many cancer patients and plays a vital role in cell proliferation, apoptosis, the cell cycle, DNA repair, and regulation of genomic stability." (PMID 31788446, 2019). "Nevertheless, COPS5, as well as COP9 signalosome, can be an attractive molecular target for cancer metastasis through the regulation of the SNAIL pathway." (PMID 29755680, 2018). "On the other hand, COPS5 or MYC alone is insufficient to activate genes crucial for tumor growth and invasion fully, indicating their cooperativity is indispensable in cancer development." (PMID 38974382, 2024). "In addition, high expression levels of COPS5 and COPS6 were found to predict poorer prognosis in cancer patients." (PMID 38466642, 2024). "Jab1/COPS5 as an oncogene, is aberrantly overexpressed in various human cancers." (PMID 29535627, 2018). "As we observed that the ectopic expression of non-ubiquitinated mutant SNAIL (SNAIL-3KR) enhanced the impaired invasion of COPS5 knock-down A549 cells, the ubiquitination of SNAIL at least in part affects SNAIL function and the metastatic potential of cancer cells." (PMID 29755680, 2018).
cancer (continued). "The data confirmed the important role of Jab1/COPS5 in tumorigenesis, demonstrating the potential of Jab1/COPS5 to be used as a biomarker for cancer patients, and further support that Jab1/COPS5 may serve as a potential therapeutic target in different cancers." (PMID 29535627, 2018). "It was demonstrated that COPS5-positive cells in cancer tissue were significantly higher than those in non-cancerous tissue." (PMID 29228627, 2017). "Finally, while 15 DUBs were found to be significantly dysregulated in only one type of cancer, 7 (UCHL1, USP9X, USP11, USP10, USP22, COPS5 and COPS6) displayed multiple alterations in two or more tumor types." (PMID 21283576, 2011).
tumor (91 papers, 2007 to 2025). "Overexpression of COPS5 has also been implicated in lymph node metastasis and histological tumor progression." (PMID 38466642, 2024). "Collectively, the results demonstrated that inhibition of COPS5 was significantly associated with increased tumor killing." (PMID 36135183, 2022). "On the other hand, pathways involved in ribosomal functions were associated with the COPS5 expression in the tumor tissues." (PMID 27903243, 2016). "Using the CRISPR-Cas9 system, we confirmed the tumor growth effect of COPS5, which suggests it as a novel prognostic biomarker for DLBCL." (PMID 38974382, 2024). "For example, COPS5, a c-Jun activation domain-binding protein-1, interacts with multiple tumor-related genes, including PD-L1, and involves many cell signaling pathways, such as IL6-Stat3 Signaling, TGF-β Signaling, and NF-κB Signaling." (PMID 38667328, 2024). "In tumor cell-enriched region, the expression of COPS5, DLAT, DLD, FDX1, NFE2L2, PDHA1 and PDHB in the high score group is higher than that in the low score group, while the opposite is true for DLST, GCSH and LIPT2 (P <0.05)." (PMID 36618352, 2022). "Several compounds, such as curcumin and its analogs, troglitazone, doxycycline and thiolutin, have been shown to inactivate Jab1/COPS5 and/or reduce its expression, thus attenuating tumour growth." (PMID 33550701, 2021). "As a multifunctional complex, dysregulation of Jab1/COPS5 deactivates several tumor suppressors, and activates oncogenes, promoting oncogenesis." (PMID 33292641, 2020). "Jab1/COPS5 is crucial for tumor survival and enhances the resistance of tumor cells to chemotherapy and radiotherapy." (PMID 29535627, 2018). "Animal studies confirmed that troglitazone inhibited hepatocellular carcinima cell growth and decreased Jab1/COPS5 expression in tumor tissues." (PMID 29535627, 2018). "Further, inhibition of Jab1/COPS5 cooperates with anti-CTLA4 to enhance anti-tumor T cell function and decrease tumor growth." (PMID 29535627, 2018). "Mechanistically, inflammation induced macrophages to secrete TNFα that activated tumor cell NF-κB signaling, allowing the p65 subunit to bind to the promoter and promote transcription of Jab1/COPS5." (PMID 29535627, 2018). "The ES value for the COPS5 with the tumor tissues (ES = 0.65, p = 0.02, q = 0.043) was significantly higher than that with the normal tissues (ES = 0.39, p = 0.27, q = 0.49)." (PMID 27903243, 2016). "Regardless how the COPS5 inhibitors will be developed, our data suggest that combination with ERα antagonists is probably needed to re-sensitize the refractory tumours to endocrine therapy." (PMID 27375289, 2016). "The gene expression coordination between the COPS5 gene and the mitochondrial pathways was elucidated with tumor tissues." (PMID 27903243, 2016). "In the TCGA primary tumour cohort, amplification of COPS5 is relatively focal and correlates with high COPS5 mRNA expression." (PMID 27375289, 2016). "To elucidate the tumor-associated disintegration of the COP9 gene expression in detail, we focused on the COPS5 gene." (PMID 27903243, 2016). "In contrast, genes with high |rCOPS5| in the tumor tissues were concentrated near COPS5’s chromosomal region (bottom); 56 genes out of the top 100 genes were bound to 8q." (PMID 27903243, 2016). "By cross-referring the results to gene ontology provided with DAVID, we noticed that genes with high rCOPS5 of the tumor tissues were mapped in the same chromosomal location as the COPS5 gene (8q13.2)." (PMID 27903243, 2016). "COPS5 stabilizes PD-L1 to promote the tumor immune evasion expression." (PMID 38667328, 2024). "Additionally, in vivo xenografted mouse model results showed that COPS5 silencing significantly diminished the tumor growth." (PMID 36135183, 2022). "Therefore, the clones #1 and #3 recapitulated COPS5 overexpression observed in clinical tamoxifen-refractory tumours, and were used for further studies of the mechanisms of tamoxifen-resistance." (PMID 27375289, 2016).